MZB1 (marginal zone B and B1 cell specific protein)
Description:
Associates with immunoglobulin M (IgM) heavy and light chains and promotes IgM assembly and secretion. May exert its effect by acting as a molecular chaperone or as an oxidoreductase as it displays a low level of oxidoreductase activity (By similarity). Isoform 2 may be involved in regulation of apoptosis. Helps to diversify peripheral B-cell functions by regulating Ca(2+) stores, antibody secretion and integrin activation. Acts as a hormone-regulated adipokine/pro-inflammatory cytokine that is implicated in causing chronic inflammation, affecting cellular expansion and blunting insulin response in adipocytes. May have a role in the onset of insulin resistance.
Synonyms: MEDA-7; pERp1; PACAP; HSPC190; MGC29506
Tractability: Antibody: UniProt places it where antibodies can reach, with high confidence; its Gene Ontology location is reachable by antibodies, with high confidence; UniProt predicts a signal peptide or a membrane-spanning region. PROTAC: ubiquitination databases record sites on it; its protein half-life has been measured.
Gene: Protein-coding gene on chromosome 5 (139,387,467 to 139,390,081, reverse strand). Ensembl gene ENSG00000170476.
Subcellular location: Endoplasmic reticulum lumen (Isoform 1); Secreted; Cytoplasm (Isoform 2)
Subcellular location (Human Protein Atlas): Golgi apparatus; Predicted to be secreted
Gene Ontology:
Molecular function: protein binding
Biological process: integrin activation; positive regulation of immunoglobulin production; regulation of B cell proliferation; regulation of cell population proliferation; regulation of insulin receptor signaling pathway; positive regulation of cell population proliferation
Cellular component: cytoplasm; endoplasmic reticulum lumen; extracellular region; endoplasmic reticulum chaperone complex
Genetic constraint (gnomAD): Loss-of-function variants: 10 observed, 12.68 expected, observed/expected ratio (o/e) 0.79, 90% interval 0.49 to 1.34. The upper end of that interval is the gene's LOEUF score, 1.34, which puts it in group 5 of 6, group 1 being the genes least tolerant of losing a copy. Missense variants: 246 observed, 211.42 expected, observed/expected ratio (o/e) 1.16, 90% interval 1.05 to 1.29. Synonymous variants: 99 observed, 84.82 expected, observed/expected ratio (o/e) 1.17, 90% interval 0.99 to 1.38.
Homologues: Orthologues: chimpanzee MZB1 (99% identical), macaque MZB1 (97% identical), dog MZB1 (86% identical), pig MZB1 (79% identical), guinea pig MZB1 (77% identical), rat Mzb1 (72% identical), mouse Mzb1 (71% identical), rabbit MZB1 (71% identical).
Diseases named in the same sentence as MZB1 in open-access papers:
MZB1 is named in the same sentence as 61 diseases in open-access papers, as found by Europe PMC text mining. Sharing a sentence is not in itself a finding about the gene and the disease. The quoted sentences say what the papers report.
autoimmune disease (7 papers, 2013 to 2026). A disorder resulting from loss of function or tissue destruction of an organ or multiple organs, arising from humoral or cellular immune responses of the individual to their own tissue constituents. "MZB1 is an immune-related protein, and its upregulation is associated with autoimmune diseases such as periodontitis, systemic lupus erythematosus, and multiple sclerosis." (PMID 40391075, 2025). "Emerging evidence highlights its involvement in tumor biology, inflammatory responses, and autoimmune diseases, positioning MZB1 as a potential therapeutic target." (PMID 41635820, 2026). "These insights significantly extend the current understanding of MZB1’s multifaceted roles beyond its established functions in autoimmune diseases and other malignancies." (PMID 40391075, 2025). "MZB1 has a more restricted expression pattern than IFNα, which makes it an attractive potential therapeutic target in autoimmune diseases." (PMID 33318509, 2020). "MZB1 inhibitors may cause degradation of immunoglobulin, causing apoptosis of autoantibody-secreting cells in SLE and other autoimmune diseases." (PMID 29382365, 2018). "Excessive MZB1 expression in specimens from SLE patients and BWF1 mice may indicate MZB1 is a potential marker of prolific autoantibody-secreting B cells in autoimmune disease." (PMID 29382365, 2018). "Importantly, symptoms of the 22q11.2 deletion syndrome include an increased prevalence of autoimmune disorders and B cell defects that may well stem (at least in part) from lowered miR-185 levels and concomitant uncontrolled pERp1/MZB1 function." (PMID 24489546, 2013). "In autoimmune diseases such as systemic lupus erythematosus (SLE) and rheumatoid arthritis (RA), MZB1 contributes to aberrant autoantibody and cytokine secretion." (PMID 41869442, 2026). "There were no statistically significant increases in the number of MZB1-positive cells in patients with other autoimmune diseases." (PMID 29382365, 2018).
lupus (6 papers, 2018 to 2026). "MZB1 is implicated in B cell antibody production with elevated levels reported in lymph nodes of lupus patients." (PMID 37516862, 2023). "MZB1 may enhance lupus disease progression by modulating Ca2+ homeostasis and IgM production of B cells." (PMID 39917309, 2025). "We found increased expression of MZB1 protein in SLE patient specimens as well as aged BWF1 mice specimens compared with respective controls, reflecting excessive autoantibody secretion in lupus." (PMID 29382365, 2018). "MZB1, an ER resident molecular chaperone, was overexpressed in B-cell subsets in lymph nodes from SLE patients and lupus-prone mice." (PMID 29382365, 2018). "Moreover, the silencing of the MZB1 gene with methylation described in hepatocellular and gastric cancers could be seen as a form of immunological tolerance, while MZB1 protein was increased in B-cells from patients with the autoimmune condition systemic lupus erythematosus." (PMID 32707447, 2020). "Increased intrafollicular localization of MZB1+ cells was observed in specimens from SLE patients as well as BWF1 mice compared with respective controls, suggesting the role of MZ B cells within follicles in lupus pathogenesis." (PMID 29382365, 2018).
colitis (5 papers, 2025 to 2026). Inflammation of the colon. "An earlier study reported that MZB1 (pERp1) deficiency in B cells aggravated dysbiosis during the course of DSS-induced colitis, with impaired IgA secretion in the gut and a dramatic reduction in Bacteroidota." (PMID 39543372, 2025). "Research indicate that MZB1-deficient mice are more susceptible to DSS-induced colitis." (PMID 40607383, 2025). "MZB1 also modulates inflammatory responses in conditions such as colitis and periodontitis by regulating the B cell-skewed inflammatory microenvironment." (PMID 41869442, 2026). "In vivo, loss of MZB1, the J chain, or both altered IgA abundance and form, differentially affected susceptibility to DSS-induced colitis, and reshaped gut microbiota composition." (PMID 42079662, 2026). "It is known that MZB1 promotes J‐chain binding to IgA and the secretion of dimeric IgA, but not IgG; mice lack of MZB1 had diminished secretion of IgA into the gut in response to acute inflammation and developed severe colitis." (PMID 40959459, 2025).
gastric cancer (5 papers, 2019 to 2026). A primary or metastatic malignant neoplasm involving the stomach. "In primary gastric cancer, low MZB1 expression is correlated with a higher risk of recurrence following curative resection, as MZB1’s suppressive role links its reduced levels to increased hematogenous recurrence and changes in tumor progression-related gene expression." (PMID 40391075, 2025). "Conversely, in hepatocellular carcinoma (HCC) and gastric cancer (GC), MZB1 is transcriptionally silenced due to promoter hypermethylation." (PMID 41869442, 2026). "According to previous studies, MZB1, an immunoregulatory molecule, was expressed at significantly decreased levels in gastric cancer (GC) tissues." (PMID 31877723, 2019).
lung cancer (5 papers, 2024 to 2025). A malignant neoplasm involving the lung. "The Mzb1 played an important role in antibody secretion while polymorphism of rs4513061 in Agbl1 was linked to lower lung cancer risk." (PMID 40437524, 2025). "Existing studies indicate that salidroside may upregulate miR-195, modulating the Protein kinase B (AKT) and MEK/ERK signaling pathways, or enhance miR-103-3p to target the Marginal zone B-and B1-cell-specific protein (Mzb1), thereby suppressing lung cancer proliferation and metastasis." (PMID 40978035, 2025). "Notably, certain genes, such as CTLA4, MZB1, NIP7, and BUB1B in ADC, as well as GNG11 and CCNB2 in SCC, were found to be associated with tumor size, adding a crucial dimension to our understanding of lung cancer biology." (PMID 38612418, 2024).
multiple myeloma (5 papers, 2020 to 2026). "In oncology, MZB1 is overexpressed in breast cancer (BC), lymphoma, and multiple myeloma (MM), where it is associated with enhanced tumor cell proliferation and poor prognosis." (PMID 41869442, 2026). "Except for cases of leukemia, lymphoma and myeloma where elevated levels of MZB1 may be linked to abnormalities in B cell proliferation, survival and differentiation, altered expression of MZB1 is likely to be a byproduct of passenger mutations in most types of cancer." (PMID 33668983, 2021). "Overexpression of MZB1 has been reported in patients of leukemia and lymphoma, pancreatic cancer, lung adenocarcinoma, multiple myeloma, estrogen receptor-positive breast cancer, and metastatic cutaneous melanoma." (PMID 33668983, 2021).
periodontitis (5 papers, 2018 to 2026). An acute or chronic inflammatory process that affects the tissues that surround and support the teeth. "Marginal zone B and B−1 cell-specific protein (MZB1), a novel molecule associated with periodontitis, is an endoplasmic reticulum-localized protein, and its increased expression has been associated with various human diseases." (PMID 36979821, 2023). "However, a few studies have examined the effect of MZB1 on human periodontal ligament cells (hPDLCs) in the presence of periodontitis and the mechanisms underlying this effect." (PMID 36979821, 2023). "Bioinformatics analysis revealed that MZB1 is one of the most significantly upregulated genes in patients with periodontitis." (PMID 36979821, 2023). "The immunohistochemical analysis confirmed that SSR4, MZB1 and XBP1 proteins were expressed in gingival tissue from patients with periodontitis." (PMID 29921943, 2018). "The levels of the four most highly up-regulated genes, IGLL5, SSR4, MZB1 and XBP1, were investigated in gingival RNA samples from ten subjects (six with periodontitis and four healthy controls)." (PMID 29921943, 2018).
breast carcinoma (4 papers, 2021 to 2026). "The results of study suggested that MZB1 expression plays an critical role in advanced stage of breast cancer and may be a poor prognostic marker,which interact with endoplasmic reticulum stress related pathways." (PMID 35392800, 2022). "Interestingly, DERL3 expression was found to be positively correlated with MZB1 expression in the clinical specimens from breast cancer patients, suggesting DERL3 may also participate tumor progression." (PMID 34212001, 2021).
lymphoma (4 papers, 2020 to 2026). A malignant (clonal) proliferation of B- lymphocytes or T- lymphocytes which involves the lymph nodes, bone marrow and/or extranodal sites. "MZB1 has been associated with adverse prognosis in leukemias and lymphomas." (PMID 35847718, 2020).
myocardial infarction (4 papers, 2021 to 2025). Gross necrosis of the myocardium, as a result of interruption of the blood supply to the area, as in coronary thrombosis. "This study investigated the role of Mzb1 in puerarin protection against heart injury and dysfunction in acute myocardial infarction (AMI) mice." (PMID 39206261, 2024). "Improvement in mitochondrial function during myocardial infarction through stabilization of the expression of Mzb1 was reported to attenuate the inflammatory response and delay cardiac fibrosis." (PMID 34211623, 2021).
Autoimmunity (3 papers, 2016 to 2026). The occurrence of an immune reaction against the organism's own cells or tissues. "As the expression of MZB1 is restricted mostly to B cells, MZB1 is a theoretically plausible target for therapies in autoimmunity and organ transport." (PMID 33668983, 2021). "For these reasons, Mzb1 could represent a novel druggable target in the context of autoimmunity that warrants further study." (PMID 27546286, 2016).
hepatocellular carcinoma (3 papers, 2016 to 2026). A malignant tumor that arises from hepatocytes. "In hepatocellular carcinoma, patients with high MZB1 expression were found with a better prognosis." (PMID 34212001, 2021).
ovarian carcinoma (3 papers, 2023 to 2025). A malignant neoplasm originating from the surface ovarian epithelium. "Altered expression of MZB1 in tumor cells is associated with DNA damage response and cell cycle regulation, highlighting its multifaceted roles in ovarian cancer and suggesting its potential as a therapeutic target." (PMID 40391075, 2025). "We explored MZB1’s clinical potential and found it valuable (AUC > 0.70) for diagnosing ovarian cancer." (PMID 40391075, 2025). "Using ESTIMATE, TIMER, XCELL, and CIBERSORT algorithms, we investigated the correlation between MZB1 and various immune cells in the ovarian cancer microenvironment." (PMID 40391075, 2025). "Moving forward, we anticipate that further research will clarify the specific mechanisms by which MZB1 influences ovarian cancer progression, ultimately advancing its clinical translation and application in ovarian cancer treatment." (PMID 40391075, 2025). "In conclusion, MZB1 can inhibit tumor cell proliferation and migration, thereby impacting ovarian cancer prognosis and correlating with immune infiltration." (PMID 40391075, 2025). "Our study elucidates the multifaceted roles of MZB1 in ovarian cancer cells and the TIME, providing experimental evidence that supports its potential as a therapeutic target." (PMID 40391075, 2025). "In TCGA tumor samples, ovarian cancer had the highest frequency of MZB1 genetic alterations, primarily amplifications." (PMID 40391075, 2025). "Single-cell analysis of the ovarian cancer dataset GSE154600 showed MZB1 expression in both ovarian cancer cells and immune cells, predominantly plasma cells, with relatively lower expression in tumor cells." (PMID 40391075, 2025). "MZB1 exhibited broader expression in ovarian clear cell carcinoma compared to other ovarian cancer types, highlighting the importance of further investigating its role in this particular subtype of ovarian cancer." (PMID 40391075, 2025). "High MZB1 expression is an independent favorable prognostic factor, also attributable to its positive regulation within the ovarian cancer immune microenvironment." (PMID 40391075, 2025). "The present study establishes MZB1 as a novel prognostic biomarker and therapeutic target in ovarian cancer through multi-omics analyses and experimental validation." (PMID 40391075, 2025). "While research on MZB1 in cancer-related diseases holds significant promise, regrettably, its role in ovarian cancer remains unexplored." (PMID 40391075, 2025). "MZB1 in ovarian cancer cells may directly impact tumor cells, while MZB1 in immune cells may indirectly influence tumor progression by regulating the function of the respective cells." (PMID 40391075, 2025). "MZB1 holds significant clinical application potential in ovarian cancer." (PMID 40391075, 2025). "The results suggest that MZB1 may regulate ovarian cancer progression through multiple mechanisms by influencing both ovarian cancer cells and immune cells in the TIME." (PMID 40391075, 2025). "This explains the high MZB1 expression observed in bulk RNA sequencing of ovarian cancer tissues." (PMID 40391075, 2025). "This study comprehensively analyzes MZB1’s role in the TIME of ovarian cancer." (PMID 40391075, 2025). "To investigate the role of MZB1 in ovarian cancer cells, we conducted cellular assays." (PMID 40391075, 2025). "Furthermore, CCK8 and wound healing assays were performed to evaluate the impact of MZB1 on cellular phenotypes, providing insights into its functional roles and potential mechanisms in the pathogenesis and clinical prognosis of ovarian cancer." (PMID 40391075, 2025). "MZB1 expression was upregulated in ovarian cancer tissues compared to normal ovarian tissues." (PMID 40391075, 2025). "We hypothesize that MZB1 may be a critical target influencing the progression of ovarian cancer." (PMID 40391075, 2025).
ovarian carcinoma (continued). "Our analysis revealed high MZB1 expression across various ovarian cancer cell lines, particularly in OCCC, which contrasts with our understanding that MZB1 is predominantly distributed in immune cells." (PMID 40391075, 2025). "The results shown that gene MZB1, HSF1, PIK3R4, PSMB9, RSF1 and SPI1were significantly overexpressed in ovarian cancer cells SKOV-3." (PMID 40424327, 2025). "Recent studies highlight the significant role of MZB1 in shaping the tumor immune microenvironment (TIME), although its specific function in ovarian cancer remains unclear." (PMID 40391075, 2025). "The results suggest that both peripheral blood markers and TICs can be used as prognostic predictors in patients with ovarian cancer, and CXCL9, CD79A, MS4A1, and MZB1 may be potential therapeutic targets for ovarian cancer immunotherapy." (PMID 36645174, 2023).
rheumatoid arthritis (3 papers, 2018 to 2026). A chronic, systemic autoimmune disorder characterized by inflammation in the synovial membranes and articular surfaces. "Here we report that MZB1 is preferentially enriched in the pool of citrullinated lung proteins harvested from patients with rheumatoid arthritis-associated interstitial lung disease and is a substrate of PAD2." (PMID 38094295, 2023). "Additionally, MZB1+ cells were increased in synovial tissue specimens from patients with rheumatoid arthritis." (PMID 29382365, 2018). "Our data confirm the function of MZB1 in primary human plasmablasts and suggest that PAD2 promotes IgM/IgA secretion by citrullinating MZB1, thereby contributing to the pathogenesis of rheumatoid arthritis and RA-ILD." (PMID 38094295, 2023). "A significant increase in the proportion of MZB1+ cells was observed in lymph nodes from SLE patients and synovial tissue from rheumatoid arthritis patients compared with control lymph nodes and tonsils (p < 0.05)." (PMID 29382365, 2018).
interstitial lung disease (2 papers, 2022 to 2023). A diverse group of lung diseases that affect the lung parenchyma. "Notably, evidence is accumulating which also argues for significant autoimmune features in IPF: A recent proteomic study has revealed increased numbers of MZB1-positive plasma cells and higher IgG levels in tissue of patients suffering from various interstitial lung diseases (ILD) including IPF." (PMID 35456020, 2022).
lung fibrosis (2 papers, 2022). "LRG1 seems a good biomarker for pulmonary fibrosis, while MZB1 is a good biomarker for extensive skin fibrosis." (PMID 36277429, 2022). "As for the associations with Ssc clinical features, LRG1 proved to be a good biomarker for pulmonary fibrosis, while MZB1 proved to be a good biomarker for extensive skin fibrosis." (PMID 36277429, 2022). "Additionally, MZB1 proved to be a good biomarker for pulmonary fibrosis diagnosis in Ssc patients." (PMID 36277429, 2022). "Patients with pulmonary fibrosis expressed higher LRG1 and MZB1 concentrations." (PMID 36277429, 2022). "Patients with Ssc with extensive skin fibrosis, presence of daily Raynaud’s phenomenon, dcSSc and pulmonary fibrosis had higher MZB1 concentrations compared to Ssc patients without the clinical characteristic." (PMID 36277429, 2022).